CD4 (CD4 molecule)
Diseases named in the same sentence as CD4 in open-access papers (continued):
Sharing a sentence is not in itself a finding about the gene and the disease.
infection (continued). "CD4 cell counts below 350 cells/μL were associated with an increased risk of NADMs and ADMs, as did infection, smoking, and body mass index-related malignancies." (PMID 38092042, 2024). "First, we identified six epidemiological cohorts in which associations between multiple variant infection, viral load and CD4+ T cell decline had previously been investigated." (PMID 39471873, 2024). "Summary of the cohort characteristics and key results from studies that have analysed the association between CD4+ T cell decline and infections initiated by multiple founder variants." (PMID 39471873, 2024). "The Th1/Th2 balance of CD4 + T cells is crucial in cellular responses, and skewed distribution towards Th2 cells increases the risk of severe infection and vaccine-associated enhanced respiratory disease." (PMID 38806644, 2024). "We report seven patients aged 5–61 years from five families of four ancestries with autosomal recessive CD4 deficiency and a range of infections, including recalcitrant warts and Whipple’s disease." (PMID 38557723, 2024). "All CD4+ cell infections with single-mutated viruses all performed below baseline (range: 14.2–91.1%)." (PMID 39006742, 2024). "Among the causes is the direct infection of HIV-1 in gut-resident CD4+ T cells, causing a cascade of phenomena resulting in the instability of the gut mucosa." (PMID 38426062, 2024). "For all participants, there was a decline in CD4 + T cell count over the first year of infection and there was a significant correlation (p = 0.046, r = -0.59) between CD4 + T cell loss and increased PSV EE." (PMID 39251948, 2024). "A significant association was observed between SNP rs2069705 and the CD4+ T-cell count in the individuals with HIV mono-infection." (PMID 39066175, 2024). "The global burden of infections due to the pathogenic fungus Cryptococcus is substantial in persons with low CD4+ T-cell counts." (PMID 38980038, 2024). "Cell tropism in HIV‐1 is influenced by the usage of co‐receptors, with CXCR4 primarily facilitating infection in CD4+ T cells, while CCR5 is mainly associated with macrophage infection." (PMID 39319247, 2024). "HTLV‐1, the first human retrovirus discovered, mostly infects CD4+ T cells, causing a lifelong mostly symptom‐free infection, with only about 5% developing adult T‐cell leukemia/lymphoma (ATLL)." (PMID 39240588, 2024). "Both log10 SpVL and the time to a clinically significant CD4+ T cell count, showed significantly greater variation in multiple variant infections than infections initiated by a single variant across risk groups." (PMID 39471873, 2024). "HIV infection results in drastic CD4+ T cell depletion, either caused by direct cell lysis following productive infection or by CD8+ T cell-mediated killing of infected cells." (PMID 38400997, 2024). "Although HIV infects various cell types in the host organism, CD4+ T cells are preferentially targeted since they are highly permissive towards productive infection, concomitantly bringing about the hallmark immune dysfunction that accompanies HIV-1 spread." (PMID 38543785, 2024). "The role of CD4+ T cells in either resistance or susceptibility of different strains of mouse to infection with L. major has been established by several groups in the early 1980s." (PMID 38469319, 2024). "Specifically, male gender, age over 30, heterosexual infection (HETs), long-term infection, CRF01_AE, and Pre-treatment CD4 T cell counts below 350/μL were identified as risk factors impeding CD4+T lymphocyte recovery." (PMID 38994006, 2024). "Since CD4+T cells are closely associated with the body’s immune function, we further analyzed the association between CD4+T cells and multiple infections." (PMID 38774626, 2024). "Uncontrolled VLs and decreased CD4+ T-cell counts within a few weeks following infection are hallmarks of pathogenic HIV/SIV." (PMID 39066199, 2024).
infection (continued). "Viruses lacking M78, an immune factor that degrades MHC-II in infected cells, exhibit a diminished ability to colonize SGs following i.n. infection, and this effect can be partially rescued with CD4 T-cell depletion or using mice deficient in MHC-II." (PMID 39134803, 2024). "In MSM-receptive transmissions, the time to a clinically relevant CD4+ T cell count for single variant infections was 9.96 years, compared with 9.92 years for infections initiated by multiple variants." (PMID 39471873, 2024). "In humans, T cells seem to play a major role in disease pathogenesis but are also associated with clearance of Ct infection, driven by CD4 T cell-derived IFN-γ." (PMID 39093884, 2024). "Lower NK cell or CD4+ T-cell count, mycophenolate use, and lower eGFR positively correlated with the risk of severe infection." (PMID 39660122, 2024). "By analyzing CD4+ T cell specificity to the HA118-132 epitope and HA IgG titers, it was found that CD4+ T cell and Ab responses to the vaccination were closely associated with a person’s infection and vaccine history." (PMID 38675771, 2024). "In line with this concept, we found that a higher percentage of CD4 T cells at baseline was associated with a higher likelihood of infections during follow-up." (PMID 38689880, 2024). "These distinct responses to infection and vaccination likely explain the substantially higher neutralization titers associated with infection, as well as the CD4+ T cell-biased response to vaccination." (PMID 38318179, 2024). "Infection rate in baricitinib trials was associated with decreased NK and CD4 T-cell counts, whereas for tofacitinib correlates were seen with overall lymphocyte count decreases but no particular subset." (PMID 39403378, 2024). "Pediatric HIV infection, like adult infection, is associated with gut microbial dysbiosis, loss of gut epithelial integrity, bacterial translocation, CD4 + T cell depletion, systemic immune activation, and viral reservoir establishment." (PMID 39425183, 2024). "We also found that the difference in time to a clinically relevant (≤350 cells mm−3) CD4+ T cell count between multiple and single variant infections varied slightly across risk groups." (PMID 39471873, 2024). "In immunocompromised individuals with HIV, however, the ultimate destruction and reduction in CD4+ T cells weakens the ability of the host immune system to respond effectively to infection with Mtb, predisposing individuals with HIV to concurrent TB." (PMID 38543687, 2024). "Although we likewise observed broad increases in CCR5 expression frequency across all three tissue types following menopause, elevated CCR5 expression was only associated with increased CD4+ T cell infection frequency in the EM." (PMID 39872519, 2024). "Both post-infection timepoints are associated with significant declines in peripheral CD4 counts and correspond with SIV peak and viral setpoint, respectively." (PMID 39229223, 2024). "Given the specificity of the IL-18 response, we next examined IL-18 receptor (IL-18R) expression to begin to understand why IFN-γ production is strongly impaired in splenic CD4+ T cells in Il18-deficient mice at day 8 post-infection." (PMID 39446964, 2024). "Using these models, we were able to infer the extent to which SpVL or CD4+ T cell decline varied as a function of the probability that infection was initiated by multiple variants in a risk group stratified population of people living with HIV." (PMID 39471873, 2024). "In both male-to-female and PWID transmissions, however, the median time to a clinically significant CD4+ T cell count in multiple variant infections was the same as that for single variant infections (10.7 and 10.9 years, respectively)." (PMID 39471873, 2024). "HLTF is degraded by virion-associated HIV-1 Vpr early after infection in HeLa cells, the CD4+ T-cell lines: Jurkat and MT4 and in hMDMs." (PMID 39205287, 2024).
infection (continued). "Following L. major infection, some mouse strains develop CD4+ Th1 cell-mediated resistance, whereas other strains show a CD4+ Th2-mediated response and are very susceptible to infection." (PMID 39201440, 2024). "It is therefore difficult to conclude that the decrease in CD4 can certainly be caused by an infection." (PMID 38416109, 2024). "Of interest, the significantly reduced bacterial loads in the ICOS−/− mice during the later time points of the infection are associated with increased numbers of IFN-γ+ CD4+ T cells in the spleens of these mice." (PMID 39682747, 2024). "For the PR8(1°)PR8(2°) group, prior studies have shown poor recall of memory CD4+ cells during homologous secondary infection, likely causing the higher ratio of HA-specific GC B cells to antigen-specific GC Tfh cells." (PMID 39283916, 2024). "The immunity of the host and the decrease in CD4+ T-cell count were found to the main factors which decide the susceptibility and the severity of infection." (PMID 39534184, 2024). "IgG <600 mg/dL, C3 <80 mg/dL, C4 <18 mg/dL, NK count <30 cells/μL, and CD4 count <350 cells/μL were all associated with a significantly higher risk of infection, and these five parameters were used to derive the immunological score." (PMID 39660122, 2024). "In an observational study that compared neurobehavioral disturbance of 34 individuals before and shortly after HIV acquisition, apathy and executive dysfunction were exacerbated following the infection and were in association with lower CD4+ T-cell counts." (PMID 39066244, 2024). "Between days 4 and 5 post-infection, the dominating immune response switched, with virus-specific CD4+ T cells increasing and appearing most closely linked with infected cell lowered viral load." (PMID 39575237, 2024). "Transferred receptors confer cell migration and adhesion properties, and macrophage-derived membrane patches render resting CD4 T cells susceptible to infection by serving as hotspots for HIV-1 binding." (PMID 38579727, 2024). "Of the four epidemiological cohorts in which a significant association between viral load and multiple variant infection was identified, a further association with lower CD4+ T cell count or faster CD4+ T cell decline was established in two." (PMID 39471873, 2024). "While our data indicates that CD4 expression is associated with infection of mucosal Vδ1 T cells, how peripheral Vδ1 T cells become infected is still an outstanding question due to the low or absent expression of CD4." (PMID 39149467, 2024). "When looking only at infections, a higher percentage of baseline CD4 T cells was associated with the occurrence of infection during follow-up (per %: OR 1.14, CI: 1.05–1.25, p < 0.001)." (PMID 38689880, 2024). "In this study, we test this assumption by first summarising the existing evidence for an association between infections initiated by multiple variants and faster CD4+ T cell decline." (PMID 39471873, 2024). "In the HIV/AIDS population, prophylaxis decisions are decided based on a patient’s CD4+ count or risk of infection recurrence." (PMID 39459894, 2024). "The CC genotype was associated with lower CD4+ T-cell counts in individuals with HIV mono-infection." (PMID 39066175, 2024). "Although its etiology is not fully understood, there are multiple risk factors for brain aging, such as infections, advanced age, low CD4+ T cell nadir, a history of more severe immunosuppression, and possibly the use of ART." (PMID 39685490, 2024). "The presence of circulating CD8+ T cells is associated with the acute phase of infection, whereas CD4+ T-cell responses develop at a later stage of infection." (PMID 39104592, 2024). "Even relatively small studies have demonstrated a relationship between CD4/CD8 T-cell ratios at or below 0.3 with increased infection and cancer risk." (PMID 39728019, 2024). "Higher CD4 counts (>500 cells/mm3vs. <200 cells/mm3) were associated with a reduced risk of breakthrough infection." (PMID 37821620, 2024).
infection (continued). "For HIV-infected patients who are at risk for mpox infection, clinicians should make reasonable prophylactic and therapeutic recommendations based on the patient’s clinical status, viral suppression, and CD4 cell count." (PMID 39010029, 2024). "Instead, it is associated with the levels of target cells for infection (CD4 + CCR5 + T cells), particularly in the oral and upper gastrointestinal tract tissues." (PMID 38227162, 2024). "Applying our model framework to simulated risk group-stratified transmission pairs, we inferred relationships between the probability that infection is initiated by multiple variants, recipient log10 SpVL and the rate of CD4+ T cell decline." (PMID 39471873, 2024). "A decrease in the number of CD4 cells over time indicates a worsening of the immune system and higher susceptibility to infection." (PMID 39211944, 2024). "As a second exploratory objective we correlated CD4+-T-cell numbers with the frequency of infections to assess a possible impact on the risk of infections." (PMID 37152008, 2023). "Both in susceptible and young protected groups, ZEB2+ memory CD4+ T cells were significantly expanded during the infection compared to convalescence." (PMID 38001069, 2023). "It is likely that the severe reduction of combined CD4+/CD8+ T cells in these birds left them susceptible to respiratory or other types of infections." (PMID 36992357, 2023). "Of 67 HIV-1 infections, considering factors associated with continued CD4+ T cell count, there were 41 infections with CRF01_AE and 26 infections with CRF07_BC." (PMID 37152735, 2023). "Our study demonstrated that a linear relationship between CD4 count and surgical site infection risk." (PMID 37497209, 2023). "Multiple studies have implemented CyTOF to define the features of CD4 + T cells most and least susceptible to infection [5••, 6•, 9••, 10–12]." (PMID 36689119, 2023). "Several experimental studies on Cryptosporidium have linked the cell-mediated immune responses, especially the CD4+ T count, to the susceptibility to infection and severity of the disease." (PMID 37858196, 2023). "Because of the xeno-MHC environment in the mouse, most human CD4+ T cells were highly activated and thereby susceptible to infection from newly released virions." (PMID 36680242, 2023). "Upon analysis of infection efficiency by sex, we showed that the CD4+ T cells derived from men displayed an increased susceptibility to HIV within the most permissive 24–72 h time window." (PMID 38067117, 2023). "These DCs are present at a low frequency in the anorectal tissue, but it is known that they express coreceptors CCR5 and receptor CD4, making them susceptible to infection." (PMID 36798134, 2023). "In this study, we evaluated the SARS-CoV-2-specific humoral and the CD4+ T cell response to selected viral variants upon natural infection and following vaccination in a Colombian population." (PMID 37575243, 2023). "Mice vaccinated with TAS2010 developed immunity systemically and were protected against gut-associated virulent infection in a CD4+ T cell-dependent manner." (PMID 37733817, 2023). "The study found that the risk of Bh infection decreases rapidly with increasing CD4+ T cell counts, and after reaching 500 cells/μl, Bh infection risk remains consistently low level." (PMID 37697423, 2023). "The significant increase in CD4+ cells from baseline to day 4 post-infection in both the ‘young’ and ‘older’ hamsters is likely caused by lymphocytes moving towards the site of infection in the upper respiratory tract." (PMID 37242338, 2023). "A major disadvantage of CD4-based CAR-T cells is their susceptibility to infection by HIV, given that CD4 is the natural ligand for the gp120 envelope protein of HIV." (PMID 36992496, 2023). "The results showed that consciousness disorder, WBC count, neutrophil levels, and CD4+ T-cell counts <300/μL were independent risk elements of early infection in patients." (PMID 37360336, 2023).
infection (continued). "E-value analyses was conducted to find the robustness of associations between Bh infection and CD4+ T immunological status, HIV virological status and treatment interruption." (PMID 37697423, 2023). "In an M. tuberculosis infection model, loss of Bhlhe40 expression, specifically in CD11c+ cells, resulted in susceptibility of these mice to this infection, similar to what occurs in the Bhlhe40fl/fl-Cd4-cre mice." (PMID 37843306, 2023). "After competitive T cell transfer, CD4+ T cells heterozygous for Irf4 mutation were already impaired in generating Th2 and Th17 cells responses to infection and in their accumulation in the intestinal tract of recipient mice." (PMID 37469513, 2023). "These LTNP-EC HIV-1 Envs are therefore ineffective in ensuring productive CD4-dependent viral fusion, transfer, and infection, directly correlating these deficient viral signals and functions to the LTNP-EC clinical outcome." (PMID 37685911, 2023). "The hallmark of infection with the human immunodeficiency virus (HIV) is the progressive destruction of CD4+ T cells in both count and function, particularly the activated CD4+ T cells." (PMID 37608956, 2023). "In previous investigations on the initial phase of TMEV-infection until 7 dpi, CD4+- as well as CD8+ T cell deficient mice on a C57BL/6 background displayed a lack (CD8-/- mice) or reduced numbers (CD4-/- mice) of VP2-specific cytotoxic T cells, respectively." (PMID 37292191, 2023). "Due to substantial CD4+ T cell loss during infection, mb-TLR2 expression in jejunum CD4+ T cells was excluded from our analysis." (PMID 38140264, 2023). "HIV is characterized by a cellular immune deficiency with progressive CD4+ T cell loss, resulting in an increased susceptibility towards various infections." (PMID 36839516, 2023). "The results showed that CD4+ T-cell levels of <300/μL was an independent risk factor for early infection." (PMID 37360336, 2023). "Collectively, this study highlights mechanisms by which Brucella infection subverts B and CD4+ T cell interactions to promote host susceptibility to infection." (PMID 37721965, 2023). "We previously reported B cells require CD4+ T cells to promote susceptibility to infection, indicating that CD4+ T cell and B cell interactions are detrimental to control of Brucella." (PMID 37721965, 2023). "OX40 agonism survival extension after only two weeks of treatment during early infection suggests that this treatment causes long-term changes in CD4 T cells that can continue to improve infection outcomes months after treatment has ended." (PMID 38110410, 2023). "Our study showed that although the Bh infection risk decreases as CD4+ T cell counts range from 200 cells/μl to 500 cells/μl, the absolute risk remains significant." (PMID 37697423, 2023). "The combination of myelosuppression and already reduced CD4 count creates a uniquely higher risk of infection development over the course of treatment for this patient population." (PMID 37951907, 2023). "Nonlinear models revealed a significant L-shaped association between the Bh infection risk and CD4+ T cell counts." (PMID 37697423, 2023). "We further demonstrate the MIT-T-COVID vaccine causes significant infiltration of CD8+ and CD4+ T lymphocytes in the lungs post infection." (PMID 36969239, 2023). "Intriguingly, we found PD-1 blockade enhanced susceptibility to infection in a CD4+ T and B cell-dependent manner." (PMID 37721965, 2023). "In fact, INSTI-treatment increased CD4 T cells in the patients and, at the same time, diminished the levels of lysozyme corroborating the association among lysozyme-inmune response and infection." (PMID 37653055, 2023). "The drop in CD4+ T cell counts during primary infection led to murine death, and the loss of CD8+ T cells decreased the efficiency of fungal elimination." (PMID 36836308, 2023).